CCL5 (C-C motif chemokine ligand 5)
Diseases named in the same sentence as CCL5 in open-access papers (continued):
Sharing a sentence is not in itself a finding about the gene and the disease.
bone cancer (2 papers, 2010 to 2023). A primary or metastatic malignant neoplasm affecting the bone or articular cartilage. "To date, the upregulation of the CCL5 protein level after nerve injury and in bone cancer pain has been shown in rats and mice." (PMID 37570736, 2023). "Moreover, the intrathecal administration of an anti-CCL5 neutralizing antibody attenuates established hyperalgesia in rats with bone cancer pain." (PMID 37570736, 2023). "Among them, the insulin growth factor, the fibroblast growth factor, the interleukin Il-6, the chemokine CCL5 (RANTES) and the matrix metalloproteinases MMP-2 and MT1-MMP are few of the mediators that could have a particular role in bone tumor development." (PMID 20544017, 2010).
brucellosis (2 papers, 2017 to 2024). Brucellosis is a bacterial infection that spreads from animals to people via unpasteurized dairy products or by exposure to contaminated animal products or infected animals. "Positive controls were noted to have significantly increased expression of genes associated with the inflammatory response, including CCL5 (chemokine ligand 5), MEFV (Mediterranean Fever, codes for pyrin), SLC11A (solute carrier family 11 member 2), and TNF (tumor necrosis factor) (P < .0001)." (PMID 28943993, 2017). "Multiple activation markers, such as CD69, MKI67, CCL5, CTLA4, IFNG and GZMB, were found to be enriched in the NK cells of brucellosis patients, indicating the presence of an activated NK cell response as a distinctive feature for brucellosis patients, especially for those at the acute stage." (PMID 39135683, 2024).
Chagas cardiomyopathy (2 papers, 2016 to 2021). A disease of the cardiac muscle developed subsequent to the initial protozoan infection by trypanosoma cruzi. "Expressions of CKs and their receptors have been shown to be important prognostic markers, since CCL5 and CCL9 chemokine genes were upregulated in heart tissue from individuals with Chagas cardiomyopathy." (PMID 27688600, 2016).
Chronic colitis (2 papers, 2022 to 2024). A chronic inflammatory disease of the large intestine (colon, cecum and rectum). "Similarly, the increased gene and protein expression of CCL5 is linked to intestinal leukocyte recruitment chronic colitis in both humans and mice." (PMID 39409054, 2024).
chronic pancreatitis (2 papers, 2021 to 2024). A chronic inflammatory process causing damage and fibrosis of the pancreatic parenchyma. "The inhibition of global NEDDylation by MLN4924 obviously aggravates chronic pancreatitis by promoting CCL5-mediated M2 macrophage infiltration, and the blockage of CCL5 counteracts MLN4924-mediated chronic pancreatitis." (PMID 39697538, 2024). "Collectively, CCL5 is required for MLN4924-mediated macrophage infiltration in chronic pancreatitis." (PMID 33723230, 2021). "In summary, our studies reveal a neddylation/HIF-1α/CCL5 axis in regulating macrophage infiltration in chronic pancreatitis and further represent new ideas for therapeutic strategy and disease treatment." (PMID 33723230, 2021). "As we anticipated, the mRNA expression levels of CCL5 and M2 marker CD163 were negatively correlated with the protein level of UBE2M, suggesting the neddylation-associated modulation of macrophages in chronic pancreatitis." (PMID 33723230, 2021). "Thus, HIF-1α acts as a potent modulator of neddylation-induced CCL5 expression in chronic pancreatitis." (PMID 33723230, 2021). "Compared with normal healthy controls, UBE2M is remarkably decreased in human chronic pancreatitis tissues accompanied by increased CCL5 and CD163 (markers of M2-type macrophages), indicating the important role of NEDDylation in the pathogenesis of chronic pancreatitis." (PMID 39697538, 2024).
contact dermatitis (2 papers, 2018 to 2024). An inflammatory skin condition caused by direct contact between the skin and either an irritating substance or an allergen. "Its role in activating chemokines such as IL-8 and CCL5 in the early stages of contact dermatitis contributes significantly to infiltration of skin tissue by inflammatory cells." (PMID 30140696, 2018).
cryptococcal infections (2 papers, 2019 to 2025). "When comparing the cytokines that these cells are capable of producing with the cytokines known to be induced by cryptococcal infections in the brain, a small list is generated: CXCL10, IL6, CCL5, and IFN-γ." (PMID 40985448, 2025).
Cryptosporidium infection (2 papers, 2016 to 2023). "Studies in human intestinal ECs show that chemokines such as CCL-5, CXCL-8, and CXCL-10 are upregulated in Cryptosporidium infection, and CXCL-8 is detectable in the stool samples of children infected with cryptosporidiosis." (PMID 37110479, 2023).
cutaneous leishmaniasis (2 papers, 2021 to 2022). Leishmaniasis affecting the skin. "RANTES/CCL5, together with KC/CXCL1 and MIP-2/CXCL2 participate in neutrophil, monocyte, and lymphocyte recruitment to inflammatory focus and interfere in the persistence of cutaneous leishmaniasis lesions." (PMID 34178725, 2021).
cyst (2 papers, 2022 to 2024). A sac-like closed membranous structure that may be empty or contain fluid or amorphous material. "The chemokine profile is different compared to trophozoites, the main up-regulated chemokines are the same, but CCL4, CCL4L2, CSF1, CCL5, CXCL5, and CX3CL1 are more highly up-regulated in the cyst interaction." (PMID 35573800, 2022).
degenerative disc diseases (2 papers, 2020 to 2022). "Moreover, CCL5, AQP3 and SDC4 may improve the chemotaxis of stem cell migration for self-healing of damaged disc tissue, increase water uptake by nucleus accumbens cells, and inhibit the inflammatory response, thus delaying the process of intervertebral disc degeneration." (PMID 36506585, 2022).
Dengue hemorrhagic fever (2 papers, 2018 to 2023). A serious condition caused by Dengue virus infection. "Increased levels of TNF-α, IL-1β, IL-4, IL-6, IL-8, IL-13, IL-15, macrophage migration inhibitory factor (MIF), and chemokines CCL2, CCL4, CCL5, and CXCL10 (IP-10) among others, have been reported in patients with dengue hemorrhagic fever (DHF) when compared to dengue fever (DF)." (PMID 29986388, 2018).
diffuse large B-cell lymphoma (2 papers, 2012 to 2024). "Diffuse large B cell lymphoma released CCL5 to attract monocytes into the tumor stroma and these monocytes supported B cell survival and proliferation." (PMID 38786066, 2024). "Similarly, in diffuse large B-cell lymphoma (DLBCL), neoplastic cells recruit T cells and CD14+ monocytes by CCL-5 release, also engendering a histiocyte-enriched microenvironment." (PMID 22400028, 2012).
discoid lupus erythematosus (2 papers, 2021 to 2025). A chronic, autoimmune skin condition that manifests with a red, scaling rash, most often found on the face, ears, and scalp; these lesions often lead to permanent scarring and dyspigmentation. "Importantly, these GREM1+ fibroblasts were consistently present across CLE subtypes, including both subacute cutaneous lupus (SCLE) and discoid lupus erythematosus (DLE), with the same localization, associated chemokines (CXCL10, CCL5), and associated cell types (pDC, T cells)." (PMID 40409678, 2025).
Ductal Carcinoma (2 papers, 2011 to 2019). "Our analysis also shows higher levels of CCL5 in medullary and ductal carcinoma and in TNBC compared to non-TNBC cases." (PMID 30850664, 2019). "Hence our analysis showing higher CCL5 in BrCa (medullary and ductal carcinoma) compared to normal, higher CCL5 in TNBC compared to non-TNBC and higher CCL5 in AA compared to EA, suggests its potential contribution in shaping the tumor favoring microenvironment." (PMID 30850664, 2019).
endometritis (2 papers, 2020 to 2024). An acute or chronic, usually bacterial infectious process affecting the endometrium. "The levels of the PRLR, LTF, CLA-DRB3.2, beta defensin, TLR2, TLR4, and CCL5 genes were significantly up-regulated in postparturient goats with endometritis compared to tolerant ones, while the GPX4, GST, SOD3, CAT, and ATOX1 gene patterns demonstrated the opposite tendency." (PMID 39195794, 2024).
eosinophilic esophagitis (2 papers, 2016 to 2023). Eosinophilic esophagitis (EoE) is a chronic, allergic disease of the esophagus characterized clinically by symptoms of esophageal dysfunction (including vomiting, dysphagia, feeding disorders, food impaction and abdominal pain) which persist after treatment with proton pump inhibitors (PPIs). "Besides, IL-13 has been implicated in inflammation and remodeling by inducing chemokines (CCL-3, CCL-4, CCL-5 and CXCL-1), and IL-13 is a direct inducer of both CCL11 and CCL24 in eosinophilic esophagitis." (PMID 27533463, 2016). "The central role of the Th2 response in the pathogenesis of eosinophilic esophagitis, with the release of mediators such as thymic stromal lymphopoietin (TSLP), IL-4, IL-5, IL-13, TGFß, and eosinophil chemokines (eotaxin 1-3/CCL11-CCL24-CCL26 and RANTES/CCL5) has been demonstrated." (PMID 36902457, 2023).
fragile X syndrome (2 papers, 2017 to 2023). A genetic syndrome caused by mutations in the FMR1 gene which is responsible for the expression of the fragile X mental retardation 1 protein. "The higher levels of CCL2 and CCL5 were detected in ASD patients while lower plasma levels of these genes were detected in ASDs with fragile X syndrome." (PMID 36691005, 2023).
haemorrhagic stroke (2 papers, 2022 to 2023). "In conclusion, CCL5 may act as a diagnostic biomarker differentiating between ischemic and hemorrhagic stroke." (PMID 36077361, 2022). "CCL5 could be used as a diagnostic marker to distinguish between ischemic and hemorrhagic strokes." (PMID 36077361, 2022). "Moreover, CCL5 may act as a diagnostic biomarker distinguishing between ischemic and hemorrhagic stroke." (PMID 36077361, 2022). "Therefore, CCL5 could be used as a diagnostic marker to distinguish between ischemic and hemorrhagic strokes." (PMID 36077361, 2022). "In this study, we found that patients suffering from either ischemic or hemorrhagic stroke had very different levels of CCL5." (PMID 36077361, 2022). "CCL5 levels were lower in patients with hemorrhagic stroke than in patients with acute ischemic stroke." (PMID 36077361, 2022). "The behavior of CCL5 in hemorrhagic stroke patients is presented here, for the first time, showing a significant reduction in level compared with that in healthy subjects." (PMID 36077361, 2022). "On the other hand, in the hemorrhagic stroke patients, the CCL5 levels were significantly lower than those in the healthy subjects only in the male group (p < 0.001 at day 0, p = 0.003 at day 1, and p = 0.001 at HD)." (PMID 36077361, 2022). "Surprisingly, in hemorrhagic stroke, the decrease in CCL5 levels is more pronounced in males than in females." (PMID 36077361, 2022). "In the hemorrhagic stroke patients, neurological severity at admission had no influence on CCL5 levels." (PMID 36077361, 2022).
helminth infection (2 papers, 2017 to 2022). "Interestingly, helminth infections are associated with high levels of CCL5, among other pro-inflammatory chemokines, and in particular, by DCs." (PMID 28360908, 2017). "Thus, the down-regulation of CCL5 in high-diarrhoea sheep complements an overall suppression of the immune response to helminth infection." (PMID 35140270, 2022).
hematoma (2 papers, 2022 to 2023). A hematoma is a collection of blood from a vascular structure into an extravascular space. "In the same study, a positive association between hematoma fluid CCL5 (also termed regulated on activation, normal T-cell expressed and secreted, RANTES) levels and recurrence as well as a negative association between IL-5, IL-13, IFN-γ and CXCL10 levels and recurrence was also indicated." (PMID 37510193, 2023).
hemolytic-uremic syndrome (2 papers, 2022). Acute kidney injury associated with microangiopathic hemolytic anemia and thrombocytopenia. "Upregulation of CCL2 and CCL5, and to a lesser extent CCL3, was also shown to mediate the accumulation of macrophages in kidney in a mouse model of the hemolytic-uremic syndrome." (PMID 35203629, 2022).
hyperhomocysteinemia (2 papers, 2021 to 2022). A serious metabolic condition caused by mutations in the MTHFR gene, medications, or nutritional deficiency. "Moreover, knowing that hyperhomocysteinemia is a risk factor for osteoporotic fractures, another previous study indicated that the protein CCL5 could be generated in osteoblasts after homocysteine induces serum amyloid A3." (PMID 35659283, 2022).
hypertrophy (2 papers, 2021 to 2026). Hypertrophy is the increase in the volume of an organ or tissue due to the enlargement of its component cells. "Cardiac hypertrophy promoted by Ang II, assessed via cardiomyocyte cross-sectional area, was also significantly suppressed in CCL5 KO mice." (PMID 41346713, 2026).
inflammatory bone diseases (2 papers, 2025). "In addition, SCSP modulates inflammatory cascades by attenuating IL-17 signaling, Toll-like receptor pathways, and key genes implicated in inflammatory bone diseases, such as Ccl2, Il17re, Fosl1, Mmp13, Ccl5, Tlr1, Il12b, and Atp6v1b1." (PMID 40926992, 2025). "Additionally, the reduced expression of immune cell recruitment markers, including CCL3 and CCL5, points to an anti-inflammatory effect, potentially mitigating bone resorption in inflammatory bone diseases." (PMID 40711169, 2025).
ischemic cardiomyopathy (2 papers, 2021 to 2022). Ischemic cardiomyopathy is a cardiomyopathy in which a weakness in the muscle of the heart due to inadequate oxygen delivery to the myocardium with coronary artery disease being the most common cause. "We identify a pro-fibrogenic macrophage subtype in non-ischemic cardiomyopathy, and demonstrate that WWP2 is a key regulator of IRF7-mediated Ccl5/Ly6chigh monocyte axis in heart fibrosis." (PMID 36450710, 2022).
Kaposi's sarcoma (2 papers, 2017 to 2022). A malignant neoplasm characterized by a vascular proliferation which usually contains blunt endothelial cells. "Kaposi’s sarcoma cells released IL-6, IL-8, Ccl5, and Cxcl10 in response to long-term poly(I:C) exposure." (PMID 35737804, 2022). "In addition, in Kaposi sarcomas D6/ACKR2 delays tumor progression through inhibition of inflammatory chemokines CCL-2, CCL-5 and CCL-3 and reduces macrophage infiltration and angiogenesis." (PMID 28740576, 2017).
Lewis lung carcinoma (2 papers, 2022 to 2023). "For example, bone marrow-derived cells (BMDCs) secrete chemokines such as Ccl5 that potentiate metastasis, but Jdp2–/– BMDCs do not induce invasion of Lewis lung carcinoma cells." (PMID 37596694, 2023). "Bone marrow–derived cells (BMDCs) secrete chemokines such as CCL5, which potentiate metastasis; however, Jdp2−/− BMDCs do not induce a capacity for invasion in Lewis lung carcinoma cells." (PMID 33723743, 2022).
lysosomal storage disease (2 papers, 2019 to 2023). A metabolic disorder caused by mutations in proteins critical for lysosomal function, including lysosomal enzymes, lysosomal integral membrane proteins, and proteins involved in the post-translational modification and trafficking of lysosomal proteins. "In addition, in the present work, we report Ccl5/CCL5 as one of the most significantly overexpressed gene in mouse models of lysosomal storage diseases with neuroinflammation correlating with the microgliosis." (PMID 31883529, 2019).
myasthenia gravis (2 papers, 2021 to 2023). Myasthenia gravis (MG) is a rare, clinically heterogeneous, autoimmune disorder of the neuromuscular junction characterized by fatigable weakness of voluntary muscles. "While the intrathymic function of CCL5 (RANTES) is poorly understood, its expression has been implicated in myasthenia gravis, a thymoma‐related autoimmune disorder." (PMID 36925684, 2023). "More specifically, oestradiol has also been shown to repress mRNA expression of chemokines in other tissues including CCL5 in a mouse model of autoimmune encephalomyelitis and a range of inflammatory cytokines in Myasthenia gravis." (PMID 34602068, 2021).
Neonatal sepsis (2 papers, 2020 to 2025). Systemic inflammatory response to infection in newborn babies. "However, to our knowledge, there are no studies investigating sex-dependent differences of IL-2, CCL5, or IL-17 in neonatal sepsis." (PMID 32373108, 2020).
Neurofibromatosis-1 (2 papers, 2017 to 2021). "One such chemokine, Ccl5, produced by low-grade tumor-associated microglia, is responsible for maintaining neurofibromatosis type 1 (NF1) mouse optic glioma growth in vivo." (PMID 28380429, 2017).
peripheral arterial disease (2 papers, 2022 to 2023). A disorder of the arteries supplying the upper and lower extremity and the visceral organs. "In skeletal muscle, the expression of TNF-alpha, INF-gamma, IL-17A, IL-6, CCL5, and TGF-beta were increased in patients with peripheral arterial disease (PAD)." (PMID 36579591, 2022).
peripheral nerve injury (2 papers, 2022 to 2023). Injury to a peripheral nerve. "Our research is the first comprehensive behavioral and biochemical study showing that many endogenous ligands of CCR1 (CCL2/3/5/7/8/9) and CCR3 (CCL5/7/8) are significant in the development (CCL2/3/5/7/8/9) and maintenance (CCL2/7/8) of neuropathic pain after peripheral nerve injury in mice." (PMID 36611891, 2022).
Periportal fibrosis (2 papers, 2012 to 2018). The presence of fibrosis affecting the interlobular stroma of liver. "RANTES (CCL5), another monocyte/macrophage-derived chemokine which has a central role in the regulation of both Th1 and Th2 responses by controlling the migration and activation of leukocytes on the site of inflammation, was found to negatively associate with periportal fibrosis." (PMID 30546364, 2018).
phyllodes tumor (2 papers, 2023). A benign, borderline, or malignant fibroepithelial neoplasm arising from the breast and rarely the prostate gland. "Additional research indicates that an established positive feedback mechanism involving CCL5 and CCL18 between M2 macrophages and myofibroblasts contributes to the malignant progression of phyllodes tumors." (PMID 37671155, 2023).
pneumococcal infection (2 papers, 2015 to 2018). Infections with bacteria of the species streptococcus pneumoniae. "Furthermore, inhibiting IL-10 resulted in an increase in CCL3 and CCL5, two of the chemokines that were increased in aged mice following pneumococcal infection." (PMID 25595646, 2015). "In addition, the expression of CCL5, an important chemokine, which attracts neutrophils in pneumococcal infections, was strongly upregulated in re-stimulated PLY-liposome-induced macrophages, whereas controls did not induce CCL5 expression." (PMID 30100903, 2018).
polyp (2 papers, 2011 to 2022). A usually exophytic mass attached to the underlying tissue by a broad base or a thin stalk. "Specifically, CCL19 and CCL5 had reduced expression in polyp lesions." (PMID 21249124, 2011). "Similarly, decrease in CCL5, CCL21 and CXCL12 chemokines are related with reduced cell adhesion which could enhance invasive character for polyp." (PMID 35486660, 2022).
primary biliary cirrhosis (2 papers, 2021 to 2022). "Increased levels of CCL5 have been observed in patients with primary biliary cirrhosis." (PMID 35204421, 2022).
pulpitis (2 papers, 2024). Inflammation of the dental pulp. "In experimentally induced rat pulpitis, the kinetics of CXCL1 (GROa), CXCL2 (GROb), and CCL2 (MCP1) mRNA expression correlates with the infiltration of neutrophils, and CCL5 (RANTES) mRNA expression correlates with the infiltration of macrophages." (PMID 39917698, 2024).
retina degeneration (2 papers, 2012 to 2020). "Compared to WT retina, RCS retina contained 3.4-fold higher levels of CCL5 transcripts at P14 as compared to ~2-fold higher levels at P20, and P35, the previously recognized early and late stage of RCS retina degeneration, respectively." (PMID 32765507, 2020).